KIF21B (kinesin family member 21B)
Description:
Plus-end directed microtubule-dependent motor protein which displays processive activity. Is involved in regulation of microtubule dynamics, synapse function and neuronal morphology, including dendritic tree branching and spine formation. Plays a role in lerning and memory. Involved in delivery of gamma-aminobutyric acid (GABA(A)) receptor to cell surface.
Synonyms: KIAA0449; DKFZP434J212
Tractability: Antibody: the Human Protein Atlas places it where antibodies can reach. PROTAC: ubiquitination databases record sites on it; its protein half-life has been measured.
Gene: Protein-coding gene on chromosome 1 (200,969,390 to 201,023,714, reverse strand). Ensembl gene ENSG00000116852.
Subcellular location: Cytoplasm, cytoskeleton; Cell projection, dendrite; Cell projection, growth cone; Cell projection, axon; Cytoplasmic vesicle
Subcellular location (Human Protein Atlas): Mid piece; Plasma membrane; Cytosol; Mitotic spindle
Pathways (Reactome):
Hemostasis: Kinesins
Vesicle-mediated transport: COPI-dependent Golgi-to-ER retrograde traffic
Gene Ontology:
Molecular function: ATP binding; microtubule binding; microtubule motor activity
Biological process: microtubule-based movement
Cellular component: kinesin complex; axon; cytoplasmic vesicle; cytoskeleton; dendrite; growth cone
Genetic constraint (gnomAD): Loss-of-function variants: 83 observed, 188.71 expected, observed/expected ratio (o/e) 0.44, 90% interval 0.37 to 0.53. The upper end of that interval is the gene's LOEUF score, 0.53, which puts it in group 2 of 6, group 1 being the genes least tolerant of losing a copy. Missense variants: 1,711 observed, 2,209.8 expected, observed/expected ratio (o/e) 0.77, 90% interval 0.74 to 0.81. Synonymous variants: 832 observed, 899.44 expected, observed/expected ratio (o/e) 0.93, 90% interval 0.87 to 0.98.
Homologues: Orthologues: macaque KIF21B (99% identical), chimpanzee KIF21B (99% identical), rabbit KIF21B (96% identical), dog KIF21B (96% identical), guinea pig KIF21B (96% identical), rat Kif21b (96% identical), mouse Kif21b (96% identical), pig KIF21B (95% identical), zebrafish kif21b (76% identical). Paralogues in human: KIF21A (61% identical), KIF4A (24% identical), KIF4B (24% identical), CENPE (21% identical), KIF7 (20% identical), KIF27 (19% identical), KIF13B (17% identical), KIF1A (17% identical), KIF1B (17% identical), KIF15 (17% identical), KIF13A (16% identical), KIF5A (16% identical), and 29 more.
Diseases named in the same sentence as KIF21B in open-access papers:
KIF21B is named in the same sentence as 49 diseases in open-access papers, as found by Europe PMC text mining. Sharing a sentence is not in itself a finding about the gene and the disease. The quoted sentences say what the papers report.
multiple sclerosis (7 papers, 2014 to 2023). A progressive autoimmune disorder affecting the central nervous system resulting in demyelination. "Polymorphisms in the KIF21B gene are associated with multiple sclerosis, ankylosing spondylitis, Crohn’s disease, and ulcerative colitis." (PMID 33585227, 2020). "Kinesin family member 21b (kif21b) is one of the few multiple sclerosis (MS) risk genes with a presumed central nervous system function." (PMID 25274010, 2014). "Research has linked the KIF21B gene to autoimmune conditions like multiple sclerosis." (PMID 33346730, 2020). "The KIF21B gene, which is highly expressed in the CNS, mostly in the dendrites of neurons, was previously reported to be associated with multiple sclerosis (MS)." (PMID 33384710, 2020). "Genetic variation in kinesins has also been linked to susceptibility to autoimmunity: specifically, variants in KIF21B and KIF5A have been associated with multiple sclerosis in humans, while variants in KIF1C predispose mice to autoimmune orchitis." (PMID 37895021, 2023). "Increased expression of KIF21B accelerates the progression of neurodegenerative diseases, such as Alzheimer’s disease and multiple sclerosis." (PMID 33585227, 2020). "KIF5A along with other kinesin members including KIF1B and KIF21B were significantly reduced at the mRNA level and KIF5A at the protein level in gray matter of multiple sclerosis (MS) brains." (PMID 33691783, 2021).
hepatocellular carcinoma (4 papers, 2020 to 2025). A malignant tumor that arises from hepatocytes. "KIF21B, which plays a role in cell division, is associated with poor prognosis in colorectal and hepatocellular carcinomas." (PMID 40228435, 2025). "KIF21B is upregulated in hepatocellular carcinoma and is significantly associated with prognosis." (PMID 36451772, 2022). "Patients with high expression of KIF21B have been demonstrated to have a poorer prognosis in hepatocellular carcinoma and non-small cell lung cancer." (PMID 32848739, 2020). "It has been recently reported that silencing of KIF21B could inhibit the proliferation of hepatocellular carcinoma BEL-7404 cells." (PMID 32536821, 2020). "In this study, the loss-of-function experiments manifested that silencing of KIF21B suppressed the proliferation of H1299 and A549 cells, and inhibited NSCLC tumor growth in vivo, which was consistent with the proliferation promoting effect of KIF21B in hepatocellular carcinoma cells." (PMID 32536821, 2020). "In the present study, we determined that KIF21B was up-regulated in NSCLC tissues compared to adjacent normal tissues, which was consistent with the expression pattern of KIF21B in hepatocellular carcinoma." (PMID 32536821, 2020).
Alzheimer disease (3 papers, 2016 to 2020). A progressive, neurodegenerative disease characterized by loss of function and death of nerve cells in several areas of the brain leading to loss of cognitive function such as memory and language. "Genetic variation in some members of the kinesin family, to which KIF21B the gene belongs, has been associated with neurodegenerative diseases such as Alzheimer’s disease, amyotrophic lateral sclerosis (ALS) and Huntington’s disease." (PMID 33384710, 2020). "Recent findings show that KIF21B is genetically linked to Alzheimer’s disease and multiple sclerosis." (PMID 27485312, 2016).
gastric cancer (3 papers, 2020 to 2024). A primary or metastatic malignant neoplasm involving the stomach. "And KIF21B, as a member of kinesins family proteins, also exerted important role in gastric cancer, HCC, and NSCLC." (PMID 36451772, 2022). "The functions of ZNF823, ZFP69B, SP6, KYNU, KIF21B, and TTF2 have not been reported in gastric cancer." (PMID 32848739, 2020).
glioma (3 papers, 2012 to 2022). A benign or malignant brain and spinal cord tumor that arises from glial cells (astrocytes, oligodendrocytes, ependymal cells). "Increased kif21b expression was observed in gliomas, brain tumours with a very poor prognosis, especially the glioblastoma multiforme with a survival rate of less than a year." (PMID 25274010, 2014). "KIF21B has been studied at the single-cell level in 12 kinds of cancer, including AML, ALL, CML, GBM, Glioma, AST, ODG, LUAD, MEL, RCC, BRCA, and PC." (PMID 36451772, 2022). "In the majority of glioma cell lines, 3 genes were overexpressed: KIF1C, KIF3C, and KIF21B." (PMID 23320178, 2012).
non-small cell lung carcinoma (3 papers, 2020 to 2022). A group of at least three distinct histological types of lung cancer, including non-small cell squamous cell carcinoma, adenocarcinoma, and large cell carcinoma. "However, the precise role of KIF21B in carcinogenesis of non-small cell lung cancer (NSCLC) remains unclear." (PMID 32536821, 2020).
osteosarcoma (3 papers, 2020 to 2022). A usually aggressive malignant bone-forming mesenchymal neoplasm, predominantly affecting adolescents and young adults. "KIF21B is abnormally expressed in osteosarcoma and affects the proliferation and apoptosis of osteosarcoma cells by regulating the PI3K/AKT pathway." (PMID 36451772, 2022). "RNA probes from each treatment group were hybridized with the chip to analyze the changes in the gene expression profiles of osteosarcoma cells before and after KIF21B knockdown." (PMID 33585227, 2020). "We first used bioinformatics analysis to show that KIF21B can be used as a biomarker for the diagnosis and prognosis of osteosarcoma." (PMID 33585227, 2020). "Then, we evaluated the effects of KIF21B on the proliferation and apoptosis of 143B and U2-OS osteosarcoma cells." (PMID 33585227, 2020). "We then examined the expression of KIF21B in human osteosarcoma tissues and cell lines using immunohistochemistry, western blotting, and qRT-PCR." (PMID 33585227, 2020). "To explore the impact of KIF21B on OS, we examined the expression of KIF21B in osteosarcoma tissues and cell lines." (PMID 33585227, 2020). "To further study the mechanism by which KIF21B participates in the development of osteosarcoma, we used a gene chip to identify differentially expressed genes before and after KIF21B silencing and performed bioinformatics analysis." (PMID 33585227, 2020). "It was found that KIF21B expression was significantly upregulated in osteosarcoma tissues and cell lines." (PMID 33585227, 2020). "In our research, KIF21B mainly exerted important role in notch signaling pathway, inositol phosphate metabolism, and phosphatidylinositol signaling system by KEGG enrichment analysis, which was similar with the previous study of critical role of KIF21B in osteosarcoma." (PMID 36451772, 2022). "Low KIF21B expression might indirectly increase the apoptosis and inhibit the proliferation of osteosarcoma cells through the PI3K/AKT pathway." (PMID 33585227, 2020). "In conclusion, our results indicated that KIF21B plays a key role in osteosarcoma." (PMID 33585227, 2020). "In addition, PI3K/AKT pathway agonists can reverse the regulatory effect of KIF21B on the proliferation and apoptosis of osteosarcoma cells." (PMID 33585227, 2020). "Since ECM processes and cell adhesion can have a broad relationship with the PI3K/AKT pathway, we hypothesize that the mechanism by which KIF21B regulates osteosarcoma cells through the PI3K/AKT pathway is probably related to ECM processes and cell adhesion." (PMID 33585227, 2020). "Following KIF21B silencing, we found that cell proliferation was inhibited and cell apoptosis was increased, which indicate that KIF21B may act as an oncogene in osteosarcoma." (PMID 33585227, 2020). "Therefore, we wanted to determine whether KIF21B plays a role in the development of osteosarcoma." (PMID 33585227, 2020). "KIF21B decreasing expression facilitated cell apoptosis and impeded cell growth and tumorigenesis in nude mice through the inhibition of PI3K/AKT pathway and decreasing of Bcl-2 and increasing of Bax expression in osteosarcoma." (PMID 36451772, 2022). "After knocking down the expression of KIF21B in the osteosarcoma cell lines 143B and U2-OS, we used cell fluorescence counting, CCK-8 assays, flow cytometry, and TUNEL staining to examine the effects of KIF21B on osteosarcoma cell proliferation and apoptosis." (PMID 33585227, 2020).
ankylosing spondylitis (2 papers, 2014 to 2020). An autoimmune chronic inflammatory disorder characterized by inflammation in the vertebral joints of the spine and sacroiliac joints. "Variation in the kif21b locus is also strongly associated with ankylosing spondylitis (M. Bechterew) and moderately with ulcerative colitis." (PMID 25274010, 2014).
autoimmune disease (2 papers, 2012 to 2016). A disorder resulting from loss of function or tissue destruction of an organ or multiple organs, arising from humoral or cellular immune responses of the individual to their own tissue constituents. "Taken together, our results nevertheless provide mechanistic insight into how polymorphism in other kinesins including KIF21B and KIF5A influence human autoimmune disease susceptibility." (PMID 23300462, 2012). "Kinesin family members are involved in the activation of immune cells and inflammatory responses, and autoimmune disease GWAS identified KIF21B and KIF5A as candidates for autoimmune disease genes, suggesting an immunoregulatory role for kinesin family members." (PMID 23300462, 2012).
breast carcinoma (2 papers, 2017 to 2022). "Twenty of the 27 common genes have published data presenting that these genes were associated with breast cancer, but seven genes (DUSP10, GABRA6, GABRR1, KIF21B, KLHL24, MAP2K2, and SLC10A1) might be passenger genes or have not yet been studied regarding their pathological roles in breast cancer." (PMID 28973975, 2017).
Crohn disease (2 papers, 2010 to 2020). A gastrointestinal disorder characterized by chronic inflammation involving all layers of the intestinal wall, noncaseating granulomas affecting the intestinal wall and regional lymph nodes, and transmural fibrosis. "We tested whether genes associated with Crohn's disease are also associated with ankylosing spondylitis and confirmed that the two diseases share associations at chromosome 1q32 near KIF21B, STAT3, IL12B, CDKAL1, LRRK2/MUC19, and chromosome 13q14." (PMID 21152001, 2010). "This study of genes associated with Crohn's disease has identified definite genome-wide significant association with AS of SNPs at chromosome 1q32 near KIF21B, and experiment-wise association at five other novel-AS loci including STAT3, IL12B, CDKAL1, LRRK2/MUC19, and at chr13q14." (PMID 21152001, 2010).
developmental delay (2 papers, 2016 to 2020). "Using trio whole-exome sequencing, we identified a de novo variant (NM_001252100.1, c.2032A>C, p.Ile678Leu) in the KIF21B gene in a first patient (P1) presenting with developmental delay, learning and motor disabilities, associated with isolated complete agenesis of the corpus callosum (ACC)." (PMID 32415109, 2020). "In the Olson study, KDM5B, NAV1, and KIF21B were identified as candidate genes for developmental delay from two patients with microduplications of 1q32.1, and these genes are all common to the deleted region of our patient." (PMID 26955491, 2016).
pancreatic cancer (2 papers, 2021 to 2023). "Consequently, the gene set enrichment analysis (GSEA) showed that KIF20B and KIF21B’s overexpression was associated with the immunological and oncogenic pathway activation in pancreatic cancer." (PMID 34557409, 2021). "In conclusion, KIF20B and KIF21B were highly expression in most pancreatic cancer cell lines compared to normal pancreatic cell." (PMID 34557409, 2021). "Next, we investigated the gene expression of KIF20B and KIF21B in pancreatic cancer cell lines and normal pancreatic cell." (PMID 34557409, 2021). "Ultimately, KIF20B and KIF21B were used to build a two-gene panel for predicting the survival of pancreatic cancer patients." (PMID 34557409, 2021). "Finally, real-time quantitative PCR (RT-qPCR) was utilized to investigate the expression pattern of KIF20B and KIF21B in pancreatic cancer cell lines and normal pancreatic cell." (PMID 34557409, 2021).
schizophrenia (2 papers, 2021 to 2024). A major psychotic disorder characterized by abnormalities in the perception or expression of reality. "For example, the rare variant analysis identified KIF21B, which has been associated with smoking initiation, ADHD (Cross-Disorder Group of the Psychiatric Genomics Consortium, 2013), and schizophrenia." (PMID 38464225, 2024).
astrocytoma (1 paper, 2014). "The astrocytoma cell lines U251 was stimulated with IL-1β and IFN-γ for 48 h and kif21b expression was compared between unstimulated and stimulated conditions." (PMID 25274010, 2014).
bone tumors (1 paper, 2020). "The expression of KIF21B in bone tumors and its related mechanisms have not been reported." (PMID 33585227, 2020).
brain malformation (1 paper, 2020). "Overall, we identified variants in KIF21B gene in four patients presenting with mild to severe neurodevelopmental delay associated with heterogeneous brain malformations." (PMID 32415109, 2020). "Our findings highlight the critical role of KIF21B in the regulation of processes involved in cortical development and implicate variants in KIF21B in ID and brain malformation." (PMID 32415109, 2020).
brain tumours (1 paper, 2014). "Understanding the function of kif21b in neurons and astrocytes, may shed new light on possible mechanisms to therapeutically target neurodegeneration and malignant brain tumours." (PMID 25274010, 2014).
Cognitive impairment (1 paper, 2021). Abnormal cognition is characterized by deficits in thinking, reasoning, or remembering. "Noteworthy, similarly to Kif21b knockout mice, which exhibit learning and memory deficits, our patients carrying KIF21B mutations showed mild cognitive impairment assessed with Montreal Cognitive Assessment (MoCA) test (mean 23 SD 2)." (PMID 34148545, 2021).
colorectal cancer (1 paper, 2022). A primary or metastatic malignant neoplasm that affects the colon or rectum. "In conclusion, KIF21B was an increasing expression in Colorectal cancer cell lines and tissue specimens, which was correlated with poor survival, immune infiltrates, cell growth, and metastasis." (PMID 36451772, 2022). "In this study, the TCGA data platform was used to analyze the expression of KIF21B in colorectal cancer and its impact on survival and prognosis and to provide potential molecular markers for the diagnosis and treatment of colorectal cancer." (PMID 36451772, 2022). "This study is aimed at exploring the function of KIF21B in colorectal cancer." (PMID 36451772, 2022). "However, the function of KIF21B in colorectal cancer has not been reported." (PMID 36451772, 2022).
congenital fibrosis of the extraocular muscles type 1 (1 paper, 2023). "Enhanced KIF21B expression has been associated with severe AD pathology, while KIF21A is linked to congenital fibrosis of the extraocular muscles type 1 (CFEOM1), a disease characterized by absence of motor neurons of the midbrain." (PMID 37016304, 2023).
demyelination (1 paper, 2014). "Abundant kif21b expression adjusted for the percentage of GM demyelination revealed that a rapid progression to EDSS 6.0 is independent of the percentage of GM demyelination." (PMID 25274010, 2014).
frontotemporal dementia (1 paper, 2014). Frontotemporal dementia (FTD) comprises a group of neurodegenerative disorders, characterized by progressive changes in behavior, executive dysfunction and language impairment, as a result of degeneration of the medial prefrontal and frontoinsular cortices. "Additionally, astrocytosis is mainly observed in younger frontotemporal dementia patients, and this is supportive for our findings regarding the correlation between kif21b and GFAP only in the young AD patients." (PMID 25274010, 2014).
lymph node metastasis (1 paper, 2020). "Moreover, high KIF21B expression was correlated with lymph node metastasis and tumor stage, predicting a poor prognosis of patients with NSCLC." (PMID 32536821, 2020).